IFI16 (interferon gamma inducible protein 16)
Diseases named in the same sentence as IFI16 in open-access papers (continued):
Sharing a sentence is not in itself a finding about the gene and the disease.
infection (continued). "The human interferon-inducible PYHIN proteins, AIM2, IFI16, IFIX, and MNDA, have recently emerged as critical cellular factors in mediating both intrinsic and innate immune responses to pathogen infection and tumorigenesis." (PMID 25665578, 2015). "To determine the effect of IFI16 depletion, 48 h after microporation we infected the cells with HSV-1 at a multiplicity of infection (moi) of 0.1 or 1.0 plaque forming units (pfu) per cell." (PMID 25375629, 2014). "There was a relative decrease in the mRNA expression for TNF-α, IFN-κ, IFI16, IFIT1, MDA5, and RIG-I in the CPV-2 infected keratinocytes when compared to uninfected keratinocytes at 4 days post infection." (PMID 25025687, 2014). "siRNA knockdown of IFI16, and its mouse homolog p204 led to a decrease in IRF3 and NF-κB activation and IFNβ gene induction following infection of cells with HSV-1." (PMID 21994762, 2011). "As prior reports have demonstrated that p300 can interact with and promote the acetylation of the IFI16 IDR, it remains to be determined whether p300 can use its lactyltransferase activity to modify IFI16 during infection." (PMID 39772686, 2025). "In cluster 1, OAS2, IFIT3, IFI16, and DDX58 were higher in the rmIFNγR1-Ig treated animals at day 7, despite this cluster of genes being defined as genes that are highly induced at day 3 post-infection." (PMID 38950078, 2024). "As an orthogonal approach to confirm that phosphorylation does not impact the capacity of IFI16 to bind viral DNA during infection, we performed a chromatin immunoprecipitation (ChIP) followed by quantitative PCR at 2 hpi, when viral genomes enter the nucleus." (PMID 37283074, 2023). "Only 2 of the 12 up-regulated ISGs (CXCL10 and IFI16) and 2 of the 4 down-regulated (CLDN2 and MX1) were common between HEV-3c and HEV-3f infection, suggesting that the IFN response might differ depending on the HEV subtype involved in infected swine." (PMID 38058490, 2023). "Our IFI16 phosphorylation mutant studies showed that diminished phase separation inhibited the ability of IFI16 to induce cytokine expressions, but not to suppress viral gene expression early in infection." (PMID 37283074, 2023). "A similar case occurred during an infection of CRIB cells with BoHV-1, which tested the activations of IFI16 and NLRP3 upstream of caspase 1 and found a decrease in the viral titer of cells treated with glyburide, which inhibits the indirect action of the inflammasome." (PMID 37515181, 2023). "In contrast, infection with the virulent HSV-1 strain in human corneal epithelial cells induced the NLRP3, NLRP12, and IFI16 to stimulate early inflammasome, followed by activation of caspase-1, IL-1β, and IL-18 that ultimately facilitates the recruitment of macrophage and neutrophils." (PMID 35008917, 2022). "In addition, inflammation-related genes including NLRP3, IFI16, IL6, IL1A, CXCL2, and CCL6 were upregulated, further confirming that infection by T. gondii induces a robust immune response to limit infection." (PMID 35012632, 2022). "Interestingly, IFI16 recognized the genome of HSV-1 in infected cells prior to viral gene expression, but later in infection, HSV-1 targeted IFI16 for degradation, thereby inhibiting maturation of IL-1β." (PMID 36298668, 2022). "While cGAS expression was not affected during HHV-6A or -6B infection, decreased interferon gamma inducible protein 16 (IFI16) levels were noted in both HHV-6A and HHV-6B-infected cells." (PMID 34299120, 2021). "After infection, DOX induced a time course dependent exogenesis expression of IFI16 in H9 cells." (PMID 33298947, 2020). "Moreover, the expression levels of NLRP3, NLRP12 and IFI-16 was sustained longer (i.e., until 24 h) in THP-1 cells after infection with the virulent strains." (PMID 31367214, 2019). "Discovering this HSV-1 immune evasion mechanism enabled investigations into IFI16 functions during active immune signaling via infection with mutant virus strains lacking ICP0 E3 ubiquitin ligase activity." (PMID 31337724, 2019).
infection (continued). "Upon infection with ICP0-RF, expression of the R23K mutant partially rescued both the suppression of viral protein levels and virus production, relative to R23A and R23Q IFI16." (PMID 31337724, 2019). "However, at early–late stages of infection, HCMV induces IFI16 translocation from the nucleus to the cytoplasm, thereby circumventing IFI16-mediated immune response." (PMID 31861809, 2019). "A recent report showed that constitutively expressing UL46 eliminated the accumulation of transcripts of both STING and IFI16 to block innate immunity, while the protein level of STING remained stable throughout infection with the wild-type virus or the ΔUL46 virus." (PMID 31113902, 2019). "Therefore, IFI16, MNDA, and HLA-DR are indeed downregulated at early times during the establishment of latency, with IFI16 showing downregulation within 24 h of infection." (PMID 31796538, 2019). "The high level of IFNβ production in dual free and complement oponized HIV/HSV exposed DCs failed to block the HIV infection but it is clear that it subdued the infection, seeing that the HIV infection was further elevated in DCs where the IFN-β was suppressed by inhibition of the DNA sensor IFI16." (PMID 31867020, 2019). "We further showed that WT IFI16 and each chimera construct could suppress viral protein levels during ICP0-RF infection." (PMID 31337724, 2019). "At later stages during infection (i.e., between 30% [Pol II S2P] or 50% [Pol II] coverage), signal intensities became lower and comparable with or without IFI16." (PMID 30670617, 2019). "Notably, upon infection by KSHV, EBV and HSV-1, the innate DNA sensor IFI16 interacts with the histone acetyltransferase p300 and CREB-binding protein (CBP) in the nucleus, which leads to the acetylation of IFI16." (PMID 31798565, 2019). "PML depletion did not increase the frequency of IFI16 colocalization with vDNA during either HSV-1EdU or ΔICP0EdU infection, demonstrating that PML-NBs do not competitively exclude IFI16 from binding vDNA." (PMID 29309427, 2018). "Importantly, no additional increase in virus yield was observed on Ruxolitinib treatment of IFI16 or PML depleted cells, indicative of an impaired innate immune response in these cells during HSV-1 ICP0-null mutant infection." (PMID 29309427, 2018). "In addition, IFI16 mediates IFN-γ induction and stimulates inflammatory activation in certain cell types during infection with KSHV,HSV-1 and HIV." (PMID 29743020, 2018). "HaCaT cells lacking IFI16 were also impaired in the secretion of CCL5 protein following infection with ultraviolet light-inactivated HSV-1." (PMID 28194029, 2017). "IFI16, H2B, BRCA1 and cGAS knockdown clearly demonstrate that a macromolecular complex of these molecules is necessary for STING activation and innate IFN-β response during KSHV and HSV-1 de novo infection." (PMID 27764250, 2016). "Absence of H2B didn’t affect IFI16-ASC association and cytoplasmic distribution and thus demonstrating that IFI16-H2B complex is independent of IFI16-ASC-procaspase-1-inflammasome complex formed during infection." (PMID 27764250, 2016). "Live-cell imaging reveals a multiphasic IFI16 redistribution, first to viral entry sites at the nuclear periphery and then to nucleoplasmic puncta upon herpes simplex virus 1 (HSV-1) and human cytomegalovirus (HCMV) infections." (PMID 27935834, 2016). "KSHV infection induces IFI16-mediated IL-1β and IFN-β secretion during de novo infection." (PMID 27764250, 2016). "To test whether these IFI16 dynamics are common across herpesviruses, we monitored IFI16 behaviors during HCMV::gfp infection." (PMID 27935834, 2016). "Our earlier studies have shown that the IFI16-inflammsome is not induced by the infection of HMVEC-d cells with lentivirus expressing KSHV proteins which suggested that IFI16 perhaps doesn’t recognize the integrated lentvirus genome as foreign." (PMID 27764250, 2016).
infection (continued). "Indeed, fibroblasts infected with HSV display activated IFI16 and NLRP3 and secrete IL-1β early after infection, although later on IFI16 is targeted to the proteasome by ICP0, likely releasing the break that IFI16 imposes on the transcription of HSV genes." (PMID 25918478, 2015). "Collectively, these studies identify the increased nuclear acetylation of IFI16 as a dynamic essential post-genome recognition event in the nucleus that is common to the IFI16-mediated innate responses of inflammasome induction and IFN-β production during herpesvirus (KSHV, EBV, HSV-1) infections." (PMID 26134128, 2015). "KSHV infection induces only a moderate IFN-β response early during de novo infection and early lytic and latent gene products inhibit this response at later times of infection, and the role of IFI16 in IFN-β production during KSHV infection is not defined." (PMID 26134128, 2015). "When lysates from HMVEC-d cells infected with KSHV or UV-KSHV for 24 h were IP-ed with anti-acetylated lysine antibody and western blotted for IFI16, similar to live-KSHV infected cells, acetylation of IFI16 increased in a time dependent manner by infection with UV-KSHV (lanes 1–7)." (PMID 26134128, 2015). "This alteration of the histone modifications at extremely early times post-infection could be due to ICP0, VP16, IFI16, or other viral or cellular factors, or a combination." (PMID 25375629, 2014). "Expression of each gene increased over the course of infection; however, the increase was significantly further augmented in the absence of IFI16." (PMID 25375629, 2014). "TBP association with each of these regions was unchanged, regardless of infection time or the presence of IFI16." (PMID 25375629, 2014). "RNA pol II association with each of these regions was the same, regardless of infection time or the presence of IFI16." (PMID 25375629, 2014). "Consistent with our experiments with transient knockdown of IFI16, permanent IFI16 depletion led to increased HSV-1 gene expression from all temporal classes of genes over the course of 8 h of infection, though expression of all the genes increased over the course of infection in both conditions." (PMID 25375629, 2014). "Because we observed IFI16-induced differences in HSV-1 gene expression and replication during infection with wt virus, we hypothesized that there were IFI16-induced differences in the histone modifications associated with wt HSV-1 DNA." (PMID 25375629, 2014). "ChIP analysis of these cells and wild-type (wt) U2OS demonstrated increased association of RNA polymerase II, TATA binding protein (TBP) and Oct1 transcription factors with viral promoters in the absence of IFI16 at different times post infection." (PMID 25375629, 2014). "Oct1 association with each of these regions was the same, regardless of infection time or the presence of IFI16." (PMID 25375629, 2014). "The suppression of complex 1 and 2 must be due to IFI16 since infection of HELFs with AdV LacZ (used as control) does not impair the induction of the two complexes by HCMV (lanes 7 and 8)." (PMID 22291595, 2012). "Moreover, the consistent phenomena in HSV-1-infected A549 cells with IFI16−/−, indicating that IFI204 might facilitate cGAS-STING DNA sensing pathway that leads to IRF3 activation during the infection of HSV-1." (PMID 38195584, 2024). "Additionally, CDK2 knockdown also led to reduced isg54 and isg56 levels in scrambled-KO HFFs, but not in IFI16-KO HFFs during infection." (PMID 37283074, 2023). "However, a detailed characterization of in what regions, and to what extent, IFI16 binds HSV-1 genomes during infection had not been performed." (PMID 35575489, 2022). "Then, two studies found that during infection by HSV-1 (in HFF cells), KSHV (in human B lymphoma cells (BJAB- EBV-negative Burkitt’s lymphoma cell line)—or HMVEC-d) or EBV (in BJAB, latency and HMVEC-d cells), the IFI16 was bound to genomes in complex with H2B histone and with the BRCA1 protein." (PMID 35458396, 2022).
infection (continued). "Although pUL97 is found in DBs, the amount may not suffice to mediate the IFI16 phosphorylation and translocation, which is seen primarily at late stages of infection, when pUL97 is expressed to high levels." (PMID 36552792, 2022). "However, ChIP-seq experiments have not been performed with these proteins in the context of infection, and it remains to be seen if IFI16 enrichment patterns match those of another protein." (PMID 35575489, 2022). "However, during the early stages of infection with nuclear-replicating viruses, IFI16 does not appear to move to the cytoplasm, remaining predominantly nuclear." (PMID 33255247, 2020). "As we previously demonstrated that the PYD is sufficient for IFI16 relocalization to this punctate localization, we now asked whether PYD aggregation ability is necessary for this enrichment to incoming nuclear viral DNA during infection." (PMID 31337724, 2019). "Nevertheless, it was demonstrated by confocal microscopy in a recent study by the Knipe lab that IFI16 and ATRX independently localize to EdC-labelled HSV-1 genomes as early as 15 min and until 60 min post infection, but viral heterochromatin formation was independent of IFI16." (PMID 31500286, 2019). "We think it likely that this involves an unidentified lytic-phase viral gene product, which may be required for overcoming the known IFI16-mediated restriction of HCMV lytic infection and occurs as a result of ΔUS28 virus initiating a lytic infection in undifferentiated monocytes." (PMID 31796538, 2019). "Infection of human corneal epithelial cells with virulent HSV-1 laboratory strains (McKrae or 17) or with the clinical isolate KOS79 induced a significant early expression of NLRP3 and IFI16 inflammasomes, compared to a steady level of control β-actin (P < 0.05)." (PMID 31367214, 2019). "Cells lacking IFI16 also secreted less CCL5 protein 24 h post infection with MVA." (PMID 28194029, 2017). "During infection, viral nucleocapsids successfully target their cargo DNA to the nucleus, possibly activating either the canonical or noncanonical pathway, dependent on nuclear pools of cGAS or IFI16." (PMID 27935834, 2016). "It was reported that IFI16 knockdown increases the SV40 early protein level (large T antigen) in cells transfected with a (naked) plasmid DNA encoding the viral genome, but not in the infection context where viral DNA is packed with histones in the virion." (PMID 27782081, 2016). "However, assembly and disassembly of nuclear peripheral IFI16 puncta (phase 1) were observed during d109 infection, not only within the first hours but also during later hours of infection." (PMID 27935834, 2016). "However, HSV-1 gene expression is not completely abrogated in the presence of IFI16, as shown here, and by the permissiveness of most cell types to infection with HSV-1." (PMID 25375629, 2014). "However, DNA sensing is not restricted to the cytoplasm, as IFI16 has also been demonstrated to bind herpesvirus DNA in the nucleus during early stages of infection to induce IFN-β expression." (PMID 23807710, 2013). "Furthermore, we found that IFI16 is upregulated by type I IFN and by the nuclear factor kappa B (NF-κB)-activating TLR7/8 agonist R848; yet, it is only slightly upregulated by HSV-1 during very early infection." (PMID 23062757, 2012). "To explain these discrepancies, we performed kinetic experiments in which IFI16-knockdown HELFs (i.e. IFI16-silenced using siRNA) were infected with HCMV at two different MOI (0.05 and 1, respectively) and the viral yield evaluated at different time points post infection (hpi)." (PMID 22291595, 2012). "However, IFI16 knockdown did not consistently reduce CCL3 protein levels after 20 h of infection (data not shown)." (PMID 23062757, 2012).